SPP1 (secreted phosphoprotein 1)
Diseases named in the same sentence as SPP1 in open-access papers (continued):
Sharing a sentence is not in itself a finding about the gene and the disease.
glioma (continued). "In conclusion, dysregulated SPP1/HMOX1 expression was strongly related to glioma WHO grades and worse outcomes, providing deeper insights into glioma therapeutic targets and oncolytic virus‐based treatments." (PMID 40495644, 2025). "SPP1/HMOX1 was involved in influencing glioma cell motility through the PI3K/AKT, JAK–STAT and syndecan 1 signalling pathways." (PMID 40495644, 2025). "Our findings highlight the importance of SPP1/HMOX1 overexpression in glioma, suggesting a potential correlation between SPP1/HMOX1 expression and IDH status in glioma." (PMID 40495644, 2025). "In glioma, SPP1 plays as a chemokine that drives the infiltration of TAM to suppress anti-tumor response." (PMID 40303328, 2025). "Analysis of gene/protein expression levels and clinical significance was performed to identify the roles of SPP1/HMOX1 using TCGA‐glioma data." (PMID 40495644, 2025). "Taken together, these results suggest a potential oncogenic role for SPP1+TAM in promoting glioma development." (PMID 38515213, 2024). "SPP1 was also reported to promote the infiltration of TAMs in glioma, which is similar to our results in B4GALNT1-overexpressing HCC cell lines." (PMID 39616302, 2024). "For example, studies have shown that infiltrating tumor-associated macrophages promote tumor growth partly by secreting SPP1, which can promote glioma cell survival and angiogenesis." (PMID 38255198, 2024). "Myeloid/microglial cells can communicate with MAN1C1-expressing glioma cells via signals produced (SPP1, GRN, PSAP, HBEGF, LGALS9, WNT5A)." (PMID 39333557, 2024). "As a well-characterized glioma invasiveness promoter, SPP1, secreted by glioma cells, can further promote macrophage infiltration and M2-like polarization, fostering immunosuppression and glioma growth." (PMID 39143438, 2024). "SPP1 is a secreted glycoprotein that highly expressed by bone marrow-derived monocytes and is known to sustain glioma cell survival and stimulate angiogenesis." (PMID 38515213, 2024). "Previous evidence has showed that glioma cell-derived Spp1 promoted endothelial progenitor cell proliferation, migration, and tube formation." (PMID 36675807, 2023). "Angio-TAMs and LA-TAMs were observed to have shared signaling amongst both glioma types in SPP1 and MIF pathways." (PMID 38012322, 2023). "SPP1 is known to be overexpressed in many malignant tumors including glioma and regulates cell growth, proliferation, apoptosis, and migration." (PMID 37354488, 2023). "Previous research has revealed a critical role of macrophage‐mediated SPP1/CD44 signaling in glioma progression." (PMID 37194413, 2023). "A comparison of high- and low-grade gliomas revealed a subpopulation of astrocytes expressing high levels of osteopontin (SPP1) in high-grade gliomas, suggesting a correlation with poor survival among glioma patients." (PMID 37304294, 2023). "Previous studies have illustrated that tumor-associated macrophages play an important role in tumor maintenance and progression, and in particular, macrophages secrete secreted-phosphoprotein 1 (SPP1) to sustain glioma cell survival." (PMID 37158834, 2023). "Studies had shown that SPP1/CD44 signaling in the perivascular niche promotes the stem cell-like properties of glioma cells and that increased SPP1 expression induces GBM-associated macrophage infiltration." (PMID 37583898, 2023). "SPP1 acts as a CD44 ligand in glioma, promoting the production of the oncogene EPAS-1 and aggresive glioma development." (PMID 36059672, 2022). "Previous studies suggested that SPP1 promoted glioma progression by upregulating GBM-infiltrating neutrophils and macrophages, and was associated with infiltration of these cells within tumor specimens." (PMID 35067176, 2022). "Strikingly, a previouly mentioned glioma-derived molecule, Spp1 was also highly expressed in GBM-infiltrating CD14+ BMDM." (PMID 36555253, 2022).
glioma (continued). "In PTEN-null GBM models, TAMs secreted SSP1 (secreted phosphoprotein 1), which sustained glioma cell survival and stimulates angiogenesis." (PMID 35600367, 2022). "q-PCR was conducted to prove that mRNA expression of Spp1 and CDH2/N-cadherin are down-regulated by probiotic combination in glioma mice (Spp1, p < 0.05; N-cadherin, p < 0.05)." (PMID 36147842, 2022). "SPP1/CD44 signaling of the glioma-infiltrated macrophages was shown to interact with the glioma cells and induce mesenchymal glioma formation." (PMID 35884391, 2022). "The KM curves showed that patients with a higher expression of SPP1 had worse OSs in many tumors, including adrenocortical carcinoma, cervical carcinoma, head and neck carcinoma, lower grade glioma, liver hepatocellular carcinoma, and pancreatic cancer." (PMID 36292645, 2022). "hBMECs co-cultured with si-SPP1 glioma cells showed attenuated network formation when compared with controls, which suggested knockdown of SPP1 inhibited angiogenesis." (PMID 36035133, 2022). "The infiltrated BMDMs secrete Spp1 which sustains glioma cell survival by inhibiting apoptosis and augmenting angiogenesis (Molecular event 19)." (PMID 36555253, 2022). "Meanwhile, the results of EdU assay suggested that SPP1 inhibited the proliferation capacity of the glioma cell lines." (PMID 36035133, 2022). "Compared with normal tissues, Cd4, Spp1 and Col3a1 expression were significantly increased in glioma tissues (Cd4, p < 0.05; Spp1, p < 0.05; Col3a1, p < 0.05), but their expression levels were not correlated with overall survival." (PMID 36147842, 2022). "We observed that circNEIL3 overexpression significantly upregulated the protein expression of SPP1, which sustains glioma cell survival and stimulates angiogenesis." (PMID 35031058, 2022). "The results, which were presented as the mean ± standard deviation (SD) of three independent experiments, suggested that SPP1 knockdown significantly reduced the viability of glioma cells (p < 0.05)." (PMID 36035133, 2022). "The marker genes for macrophage expression in glioma SPP1 and GPMB co-regulate with spot G enriching also other genes with impact for inflammation, among them CXCR4, related to glioma associated angiogenesis." (PMID 34206856, 2021). "The infiltrating macrophages secrete SPP1, which sustains glioma cell survival and stimulates angiogenesis." (PMID 34071306, 2021). "Taken together, in the present study, we established an IRRS prognostic model, composed of VEGFA, SOCS3, SPP1, and TGFB2 core DE IRGs, for risk stratification and survival prediction for glioma patients." (PMID 34497663, 2021). "We found that high SPP1 expression correlate with a shorter overall survival time of glioma patients." (PMID 34805184, 2021). "Taken together, this study provided a single-cell atlas of one high-grade glioma and revealed a critical role of macrophage-mediated SPP1/CD44 signaling in glioma progression, indicating that the SPP1/CD44 axis is a potential target for glioma treatment." (PMID 34805184, 2021). "All three SPP1 promoter SNPs at−66,−156, and−443 have been surveyed simultaneously in several diseases, including ischemic stroke, glioma, osteoarthritis, cervical spondylotic myelopathy, and a variety of cancers." (PMID 32849198, 2020). "Both tumor- and host-derived Spp1 were critical for glioma development, since ablation of Spp1 from tumor cells or induction of tumors in Spp1-/-mice resulted in prolonged survival of tumor-bearing animals." (PMID 32019108, 2020). "We found up-regulated Spp1 expression in glioma cells, but also in Cd11b+ cells (microglia and macrophages) in the rat and murine experimental gliomas." (PMID 32019108, 2020). "In vitro and in vivo cancer models showed that the induction of a stem like phenotype by SPP1 results in aggressive recurrent gliomas, by acting on Wnt signaling, cell cycle and focal adhesions." (PMID 33066172, 2020).
glioma (continued). "It has been reported that SPP1/CD44 signaling in the glioma perivascular niche promotes aggressive tumor growth, and ITGB1 was related to the dismal OS in NSCLC." (PMID 33324676, 2020). "Then, LOX recruits macrophages to infiltrate into glioma cells by binding to β1 integrin on macrophages, which secretes SPP1 to support the growth of gliomas." (PMID 33224886, 2020). "Tumor-infiltrating macrophages promote glioma cell survival and stimulate angiogenesis by secreted phospho protein 1 (SPP1)." (PMID 31799196, 2019). "The authors showed time-dependent decrease of OCT3/4, NANOG and SOX2 expression in glioma spheres after SPP1 knockdown." (PMID 28030801, 2017). "Isoforms of SPP1 displayed different effectiveness in stimulation of glioma invasion and cell survival." (PMID 28030801, 2017). "The observed regulation of SPP1 expression by stemness transcription factors led us to quantify the SPP1 mRNA levels (specifically SPP1-e, a full form of SPP1) in a subpopulation enriched in glioma initiating cells (GIC)." (PMID 28030801, 2017). "This is the first demonstration of concomitant up-regulation of SPP1 and stemness transcription factors in glioma initiating cells." (PMID 28030801, 2017). "We confirmed upregulated expression of a full form of SPP1 - SPP1-e in human glioblastomas and several glioma cell lines." (PMID 28030801, 2017). "Silencing of GLI1 expression with siRNA in human glioma cells reduced the levels of SPP1 expression and protein secretion." (PMID 28030801, 2017). "The expression of all SPP1 isoforms was increased in U87MG glioma cells, SPP1-c, -d, -e mRNA levels were upregulated in LN229 glioma cells; GBM patient-derived WG4 cells had the higher SPP1-c level in comparison to non-transformed human astrocytes." (PMID 28030801, 2017). "Knockdown of GLI1 expression in glioma cells significantly reduced the levels of SPP1 mRNA and protein production." (PMID 28030801, 2017). "The control shNeg cells expressed the similar level of Spp1 mRNA and protein as parental C6 glioma cells." (PMID 28030801, 2017). "To determine if tumour-derived SPP1 plays a role in glioma sphere formation, we knocked down its expression with the specific siRNA in cells from dissociated spheres and analysed a number of resulting secondary spheres." (PMID 28030801, 2017). "We reveal that SPP1 is overexpressed in glioma initiating cells defined by high rhodamine 123 efflux, sphere forming capacity and stemness marker expression." (PMID 28030801, 2017). "We demonstrate that even in T98G and LN18 glioblastoma cells exhibiting low levels of SPP1 expression, the expression of SPP1 is highly up-regulated in the Rhod123(–) subpopulation and glioma spheres when compared with its levels in adherent cells." (PMID 28030801, 2017). "These constructs were overexpressed in Spp1-depleted glioma cells and the efficient reconstitution of the Spp1 expression was achieved in transfected cells, as determined by qPCR at 48 h after transfection." (PMID 28030801, 2017). "C6 glioma cells stably depleted of Spp1 displayed reduced sphere forming capacity and downregulated stemness marker expression." (PMID 28030801, 2017). "A distinctive expression pattern of SPP1 isoforms was detected in a panel of human glioma cells when compared to normal astrocytes (NHA)." (PMID 28030801, 2017). "To achieve long term knockdown of Spp1, we developed C6 glioma cell lines stably transduced with lentiviral vectors carrying a control shNeg or shSpp1 (corresponding to a siRNA sequence)." (PMID 28030801, 2017). "To elucidate if the CD44 binding domain of Spp1 is critical for glioma cell capacity to self-renew, we generated constructs carrying RNA interference resistant (R) variants of a wild type Spp1 or a C-terminal truncated Spp1." (PMID 28030801, 2017). "Here we show that GAMs and not other cells of the tumor microenvironment are the predominant source for SPP1 expression in glioma." (PMID 25658639, 2015).
glioma (continued). "Silencing SPP1/HMOX1 suppressed glioma cell proliferation and promoted apoptosis." (PMID 40495644, 2025). "Elevated levels of SPP1/HMOX1 were related to poor prognosis in glioma." (PMID 40495644, 2025). "Although the traditional M1 and M2 classifications are considered to be related to the prognosis of patients with gliomas, recent single-cell sequencing revealed that glioma-associated macrophages can be further classified more precisely, such as AIF1+TAMs, SPP1+TAMs and CCL3+TAMs49." (PMID 40898016, 2025). "In addition, the elevated SPP1 and HMOX1 expression levels were found to be associated with more advanced histological subtypes of glioma, specifically when comparing GBM to astrocytoma, oligodendroglioma and oligoastrocytoma (p < 0.001)." (PMID 40495644, 2025). "As 7aaRGD is expected to block SPP1/integrin signaling, we tested its efficacy in co-cultures of primary mouse microglia with U87-MG glioma cells, which were stably transfected with either a control shRNA (shNeg) or an SPP1-targeting shRNA to achieve SPP1 gene silencing (shSPP1)." (PMID 40281508, 2025). "When SPP1 is blocked, glioma cells’ capacity to attract macrophages is greatly diminished." (PMID 41384115, 2025). "Indeed, an increase in macrophages expressing high levels of Spp1, ApoE, Apoc1, Lgals3, and Gpnmb has been documented in glioma models, with high‐grade gliomas exhibiting a greater abundance of these macrophages compared to low‐grade gliomas." (PMID 40395129, 2025). "In vitro experiments showed higher expression levels of SPP1/HMOX1 in glioma tissues." (PMID 40495644, 2025). "Moreover, single‐cell RNA sequencing analyses of glioma samples have identified a TAM subset characterised by high SPP1 expression, alongside other gene markers such as FTL, LAPTM5, S100A11, APOC1, and APOC2." (PMID 40395129, 2025). "Moreover, SPP1 and HMOX1 are directly associated with 20 key hub genes and play roles in regulating tumour progression in glioma." (PMID 40495644, 2025). "Moreover, the co‐expressed genes with SPP1/HMOX1 were subjected to a GSEA analysis in order to explore regulatory signalling pathways activated by SPP1/HMOX1 in glioma." (PMID 40495644, 2025). "Interestingly, the AIF1+TAM and SPP1+TAM were significantly more prevalent in grade 4 GBM compared to grade 2/3 gliomas." (PMID 38515213, 2024). "Interestingly, we found that most of these ligands (e.g., CSF1, CXCL8, POSTN) 21, 32, 43 are broadly expressed in different glioma subclusters, whereas SPP1 is specifically expressed in the CEBPB+ GBM subcluster." (PMID 38994023, 2024). "Both stRNA-seq and scRNA-seq indicate that BRMS1 + microglia may promote the malignant transformation of glioma cells through SPP1/CD44-mediated intercellular interactions." (PMID 39143438, 2024). "Moreover, infiltrating macrophages secrete SPP1,which maintains glioma cell survival and promotes angiogenesis." (PMID 39143438, 2024). "A similar significance of SPP1/CD44-related signals has been suggested in glioma and HCC56,57." (PMID 38521868, 2024). "The evidence also suggested that macrophage-secreted SPP1 could be an activator of HSPB1 in glioma cells and indirectly inhibit tumor cell ferroptosis." (PMID 37158834, 2023). "Previous studies demonstrated that SPP1 was able to activate AKT to promote glioma growth." (PMID 37158834, 2023). "In the U87 and LN229 glioma cell lines, we determined the role of SPP1 using in vitro experiments." (PMID 36035133, 2022). "Furthermore, it was established that GAMs and not any other cells in the tumor microenvironment were the principal source of SPP1 secretion in glioma." (PMID 35419058, 2022). "Osteopontin (OPN/Spp1), a potential biomarker for glioblastoma, could induce glioma cell migration and invasion." (PMID 36147842, 2022).
glioma (continued). "In our present study, four progression-related DE IRG (including VEGFA, SOCS3, SPP1, and TGFB2 genes)constituting a signature can perform risk stratification for glioma patients and disclosed that patients with high risk seemed to have an approximate 14.3%-29.8% 5-year survival rate." (PMID 34497663, 2021). "Collectively, these findings indicated that the macrophage-mediated SPP1/CD44 interaction might contribute to the induction of MES-like glioma cells." (PMID 34805184, 2021). "Therefore, our findings highlighted the importance of targeting SPP1/CD44-mediated macrophage-tumor cell interaction in anti-glioma treatment." (PMID 34805184, 2021). "Furthermore, downregulation of Spp1 and Mgfe8 within glioma cells inhibits the amoeboid transformation of myeloid cells and redirect M2 microglia/macrophages phenotype impairing glioma growth." (PMID 34168976, 2021). "We provided a single-cell atlas of the cellular components in this tumor, and revealed essential roles of tumor-immune cell interactions in promoting glioma progression, such as the crosstalk between macrophages and tumor cells mediated by SPP1/CD44 interaction." (PMID 34805184, 2021). "However, the macrophage-mediated SPP1/CD44 signaling in driving glioma progression has rarely been reported." (PMID 34805184, 2021). "In addition, GBM promotes macrophage infiltration by up-regulating LOX, which secretes SPP1 to stimulate angiogenesis in the PTEN-knockout GBM xenograft mouse model to sustain the growth of glioma cells." (PMID 33224886, 2020). "Some isoforms of SPP1 are in fact known to promote glioma cell invasion." (PMID 31882946, 2019). "Mechanisms of SPP1 overexpression in gliomas are poorly understood." (PMID 28030801, 2017). "Moreover, we report up-regulation of the SPP1 expression in glioma initiating cells, defined by high efflux capacities, sphere forming abilities and the upregulated expression of stemness markers." (PMID 28030801, 2017). "Our results defined mechanisms mediating SPP1 action on glioma cells." (PMID 28030801, 2017). "GLI1 knockdown reduced SPP1 mRNA and protein levels in glioma cells." (PMID 28030801, 2017). "Despite different cell sources of SPP1/osteopontin (whether SPP1 is produced by tumour or stromal cells) all presented data confirmed the important role of osteopontin-CD44 interactions in maintaining the glioma stem cell phenotype." (PMID 28030801, 2017). "However, C6 glioma cells depleted of Spp1 had reduced sphere forming capacity (> 50%) and the reduced expression of stemness factors Nanog and Oct3/4." (PMID 28030801, 2017). "The main findings of this study are: i) SPP1 overexpression in glioma initiating cells, ii) a novel mechanism of transcriptional regulation of the SPP1 by GLI1 and OCT4, and iii) demonstration of the supportive role of tumour-derived osteopontin/SPP1 in self-renewal of glioma initiating cells." (PMID 28030801, 2017). "In glioma sphere cultures undergoing forced differentiation the expression of SPP1 was reduced." (PMID 28030801, 2017). "Forced differentiation of human glioma spheres reduced SPP1 expression." (PMID 28030801, 2017). "Our data show an alternative mechanism of an autocrine action of glioma-derived SPP1/osteopontin." (PMID 28030801, 2017). "Both genes were differently expressed in glioma-associated microglia and macrophages, as invading macrophages were the major source for Gpnmb in the RCAS-PDGFb model, whereas resident microglia were the main source for Spp1 in both models." (PMID 25658639, 2015). "Macrophage-secreted SPP1 could be a potential activator for HSPB1 in glioma cells." (PMID 37158834, 2023). "Moreover, silencing of Spp1 expression in glioma cells resulted in significant reduction of tumor growth and prevented polarization of GAMs in orthotopic syngeneic rat gliomas and in human glioma xenografts in immunodeficient mice [our unpublished observation]." (PMID 32019108, 2020).